GDF15 (growth differentiation factor 15)
Diseases named in the same sentence as GDF15 in open-access papers (continued):
Sharing a sentence is not in itself a finding about the gene and the disease.
diabetes (continued). "Diabetes-free survival was shorter among participants with high baseline GDF-15 concentrations than in those with low baseline GDF-15." (PMID 30350239, 2019). "After multivariate adjustment (Model 3), the HR for diabetes in the fourth compared with the first quartile of GDF-15 was 1.43 (95% CI 1.11, 1.83; p for trend = 0.007)." (PMID 30350239, 2019). "After a follow-up of 19.0 ± 5.16 years (mean ± SD), Cox proportional hazards regression analysis was used for the study of the relationship between baseline GDF-15 and incident diabetes, with adjustment for established confounders." (PMID 30350239, 2019). "We also analyzed the association of GDF-15 with testosterone in CAD patients with hypertension, diabetes, and underwent percutaneous coronary intervention (PCI) or not, respectively." (PMID 30819257, 2019). "The HR for diabetes in the fourth compared with the first quartile of GDF-15 was 1.30 (95% CI 1.01, 1.67; p for trend = 0.061), but the association between GDF-15 (in SD units) and diabetes remained significant (HR 1.12; 95% CI 1.02, 1.23; p = 0.015)." (PMID 30350239, 2019). "The multivariate-adjusted HR for diabetes incidence was 1.43 (95% CI 1.11, 1.83; p for trend = 0.007) for the fourth compared with the first quartile of GDF-15, and was 1.17 (95% CI 1.07, 1.28; p < 0.001) per SD increase of GDF-15." (PMID 30350239, 2019). "We observed that GDF-15 levels increased as testosterone decrease after adjusting for age, hypertension, and diabetes." (PMID 30819257, 2019). "In this group, the adjusted HR for diabetes per SD increase in GDF-15 was 1.21 (95% CI 1.09, 1.35; p < 0.001), and with additional adjustment for CRP this HR was 1.16 (95% CI 1.04, 1.29; p = 0.009)." (PMID 30350239, 2019). "After adjusting for age, hypertension, and diabetes, GDF-15 decreased significantly across testosterone categories in covariance analysis (p < 0.001)." (PMID 30819257, 2019). "The multivariate-adjusted HR for diabetes per SD increase of GDF-15 was 1.17 (95% CI 1.07, 1.28; p < 0.001)." (PMID 30350239, 2019). "Although his diabetes improved with an increased dose of insulin, the growth differentiation factor-15 level gradually increased, suggesting that his mitochondrial insufficiency did not improve." (PMID 31630688, 2019). "Increased circulating GDF15 levels are also found in diabetes, cancer, cognitive impairment and cachexia patients." (PMID 30542297, 2018). "Recently, there has been increasing interest in the relationship between GDF-15 and kidney disease in diseases such as diabetes and IgA nephropathy." (PMID 29682097, 2018). "Our results showed that those with higher baseline GDF-15 levels were more likely to be male, and have a past medical history of diabetes mellitus, myocardial infarction and/or ischaemic heart disease." (PMID 27734214, 2017). "Second, we excluded those with diabetes, a major contributor to the HEART score that is associated with both CAC and GDF-15 elevation." (PMID 28245821, 2017). "In bivariate and multivariate analyses, GDF-15 levels (in tertiles) were associated with higher CHD risk by HEART score and by its components, including age, smoking and diabetes." (PMID 28245821, 2017). "An intricate interplay between renal function, anemia, and GDF-15 concentrations awaits further studies, as there are few data regarding pathophysiological role of GDF-15 in diabetes, kidney disease, and other comorbidities." (PMID 27043030, 2016). "To summarize, as data regarding pathophysiological role of GDF-15 in diabetes, kidney disease and other comorbidities are limited, associations between renal function, anemia and GDF-15 concentrations awaits further studies." (PMID 27043030, 2016). "The present study showed that pre-operative GDF-15 levels in patients undergoing OPCAB were positively associated with age, hypertension, diabetes, Scr, EuroSCOREII, NT-proBNP, hemoglobin, and plasma CRP levels." (PMID 27311391, 2016).
diabetes (continued). "In logistic regression, preoperative GDF-15, additive Euroscore, age, plasma creatinine, diabetes mellitus, and duration of cardiopulmonary bypass were independently associated with AKI." (PMID 27717384, 2016). "It is of note that the number of patients with diabetes mellitus in the present study in the highest GDF-15 tertile was almost twice as high than in the lowest GDF-15 tertile." (PMID 27717384, 2016). "The present review describes the different animal and clinical studies and patent updates of GDF-15 in diabetes and cardiovascular diseases." (PMID 26273671, 2015). "In this present review, we described all studies on GDF-15 that reports its role in diabetes and cardiovascular diseases." (PMID 26273671, 2015). "We have also looked into the potential of GDF-15 as a novel target for diabetes and cardiovascular diseases." (PMID 26273671, 2015). "The decrease in body fat was associated with a decrease in plasma leptin, FGF-21, and GDF-15 levels, and an increase in adiponectin levels, regardless of diabetes remission status." (PMID 40699839, 2025). "Furthermore, obese individuals and patients with diabetes had significantly higher GDF-15 levels compared to others." (PMID 40722664, 2025). "There was also a significant correlation with GDF-15 at follow-up (r = 0.504, p = 0.011); after correction for confounder (GFR, underlying cardiomyopathy, atrial fibrillation, and diabetes), we found an improvement in the correlation coefficient (r = 0.782, p = 0.08)." (PMID 40869494, 2025). "However, GDF15 levels were found to be increased in patients with dyslipidemia and diabetes and reduced in obese individuals." (PMID 41008541, 2025). "This connection between GDF-15 and creatinine levels is significant, as several studies have demonstrated GDF-15’s potential to predict declines in estimated glomerular filtration rate (eGFR) and mortality in patients with type 1 diabetes mellitus (T1DM) and with nephropathy." (PMID 40722664, 2025). "GDF-15 prevents hyperglycemia-induced apoptosis in diabetes mellitus." (PMID 39781722, 2025). "This discrepancy may reflect the inflammatory processes in diabetes that drive GDF15 upregulation, as GDF15 also rises in preeclampsia, depression, heart failure, and kidney injury [33,]." (PMID 40174478, 2025). "A previous study showed that the GDF-15 level was significantly higher in patients with DN than in those with diabetes without nephropathy and was associated with impaired renal function." (PMID 40362229, 2025). "It has also been reported that serum/plasma GDF15 levels could be a biomarker for diverse diseases such as diabetes, mitochondrial disorders, cardiac failures, renal failures and cancer." (PMID 41034527, 2025). "GDF-15 is induced in all cell types in response to mitochondrial and endoplasmic reticulum stress, which is commonly observed in various conditions such as cancer, diabetes, inflammation, and chronic liver and kidney disease." (PMID 40722664, 2025). "The strongest predictors of GDF-15 were age, diabetes and NT-proBNP." (PMID 37567614, 2024). "Interestingly, the opposite experiments using transgenic mice overexpressing GDF15 and treated with high fat diet and streptozotocin to induce diabetes were “protected” against the renal damages." (PMID 38892145, 2024). "Major determinants of GDF-15 were age, diabetes and N-terminal pro-B-type natriuretic peptide, although despite extensive phenotyping, only around half of the variability of GDF-15 could be explained (R2 0.51)." (PMID 37567614, 2024). "However, only age, smoking, diabetes, low physical activity, low eGFR, low LDL cholesterol, and high hs-CRP remained significantly associated with higher GDF-15 levels in the multivariable regression analysis." (PMID 39780955, 2024).
diabetes (continued). "GDF-15 was initially described as a stress-induced cytokine with elevated expression observed in various chronic and acute pathological conditions, including inflammation, cardiovascular disease, diabetes, cancer, and chronic kidney disease." (PMID 38686386, 2024). "It is noteworthy that GDF-15 is an established biomarker of diabetes and cardiovascular disease." (PMID 38828460, 2024). "GDF-15 has been linked before with glycosylated hemoglobin and poor blood glucose control in individuals with and without diabetes, suggesting a role in regulating metabolism." (PMID 39644331, 2024). "Furthermore, endogenous GDF15 is widely utilised as a biomarker for the assessment of cardiovascular disease, diabetes, cancer, cognitive impairment, cachexia, ageing, mitochondrial dysfunction and lung diseases." (PMID 39700016, 2024). "A group of serum biomarkers containing Gal-3 (BNP, Gal-3, GDF-15, sST2, OPG, miRNA 19b and 21) combined with imaging biomarkers (GLS) are going to be tested as a tool for accurately assessing the risk in AS patients with type 2 diabetes mellitus." (PMID 38002343, 2023). "Moreover, GDF-15 provided incremental prognostic value to a model, including clinical data (age, sex, BMI, smoking, hypertension, diabetes mellitus, and hyperlipidemia) (AUC 0.628 vs. 0.583)." (PMID 36676179, 2023). "Moreover, we find CRP, GGT1, GPT, and GDF15 to be highly enriched for multiple disease terms related to cardiovascular diseases and diabetes in the GLAD4U disease database." (PMID 37590326, 2023). "In contrast to ENPP7, we find that CRP, FAS, and GDF15 are the most studied targets for diabetes." (PMID 37590326, 2023). "In particular, GDF15 represents a valuable marker for hepatic fibrosis, arterial hypertension, and type 2 diabetes mellitus in obese individuals and, therefore, might be applicable in minor-invasive clinical diagnostics." (PMID 36430499, 2022). "The recent discoveries and reinterpretations of the complex functional roles of GDF-15 beyond coronary artery disease and HF, particularly diabetes and cardiometabolic conditions, have led us to conduct this meta-analysis focusing on patients with type 2 diabetes." (PMID 35883490, 2022). "Moreover, patients with diabetes had higher concentrations of GDF-15 (p = 0.017) and Troponin-T (p = 0.013), and lower concentrations of ESM-1 (p = 0.048)." (PMID 35859587, 2022). "In addition to playing important regulatory roles in energy metabolism, body weight, appetite, and immune response, GDF-15 is elevated in cardiometabolic diseases, including hypertension, diabetes mellitus, coronary heart disease, and heart failure (HF)." (PMID 35883490, 2022). "It has been suggested that administration of GDF15 therapy at the right stage of type 1 diabetes mellitus could delay clinical onset by potentially preserving the remaining β cells." (PMID 36444166, 2022). "In addition, elevated serum levels of GDF15 correlate with diabetes, chronic inflammation, infections, as well as both cardiovascular and renal diseases." (PMID 35626166, 2022). "Our analyses did not support a causal role for normal human GDF15 plasma levels with BMI, diabetes, glucose, or eBMD." (PMID 35916366, 2022). "Among healthy people, the level of serum GDF15 is very low; in contrast, the plasma GDF15 levels are significantly higher in the elderly and in patients with pathological conditions, such as coronary vascular diseases, diabetes mellitus, neurological degeneration, and cancer." (PMID 35721026, 2022). "In line with previous findings, our analysis confirmed strong correlations of GDF15 plasma levels with a range of clinical parameters (e.g. age, smoking, and BMI) and human diseases (e.g. diabetes, cardiovascular and respiratory disease), as well as several inflammatory biomarkers." (PMID 35916366, 2022).
diabetes (continued). "A previous study focusing on people without diabetes mellitus revealed that metformin treatment was associated with significantly increased levels of circulation GDF15 with lost about 3.5% of body weight." (PMID 36273168, 2022). "However, because the associations remained after excluding individuals with CVD or diabetes, it is unlikely that the disease burden captured by GDF‐15 would have substantially influenced time spent in the different activities." (PMID 35132822, 2022). "Recently, GDF-15 levels have been revealed as a robust biomarker for metformin use, which is well-recognized as the first-line medication for diabetes." (PMID 35769993, 2022). "Elevated cTnT and NT-proBNP, but not GDF-15, levels were associated with hypertension when women with diabetes and controls were analyzed separately as well (results not shown)." (PMID 35796791, 2022). "Equally important, in our entire cohort, the levels of GDF-15 were not substantially influenced by the presence of traditional cardiovascular risk factors, such as smoking, arterial hypertension, or diabetes mellitus." (PMID 36556311, 2022). "Interestingly, the optimal cut-off of HbA1c concentration for predicting high GDF-15 concentrations was 42.5 mmol/mol, which is remarkably similar to the threshold for diagnosing pre-diabetes in patients." (PMID 34663793, 2021). "Furthermore, GDF15 showed a unique pattern with elevated levels in the diabetes group at baseline which were further increased during treatment." (PMID 33279861, 2021). "In a cohort of 4360 Swedish non-diabetic individuals, GDF-15 was shown to be a strong independent predictor of risk of incident diabetes." (PMID 34217226, 2021). "The mechanism underlying the upregulation of serum NAG-1/GDF15 levels in patients with diabetes has not been elucidated." (PMID 34294853, 2021). "However, GDF-15 plasma levels were lower in the short duration diabetes group (0.82 ± 0.09 vs. 1.19 ± 0.14 ng/mL, p = 0.034, and HDL cholesterol (1.1 ± 0.1 vs. 1.4 ± 0.1 mmol/L, p = 0.043)." (PMID 33925808, 2021). "Furthermore, the prevalence of diabetes mellitus and hypertension increased markedly with increasing GDF-15 concentrations." (PMID 32993054, 2020). "The association tended to be less significant with increasing age: multivariate-adjusted HRs for diabetes per SD increase of GDF-15 were 1.24 (95% CI 1.08, 1.42), 1.19 (95% CI 1.00, 1.41) and 1.04 (95% CI 0.89, 1.23) for participants aged ≤55, 56–60 (>55 and ≤60) and >60 years, respectively." (PMID 30350239, 2019). "The association of GDF-15 with diabetes risk was generally linear (p for non-linearity = 0.363), and was not time dependent (p for time dependency = 0.051)." (PMID 30350239, 2019). "In a multivariate competing-risk model, HRs for diabetes were 1.33 (95% CI 1.03, 1.71; p for trend = 0.049) for the fourth vs the first quartile of GDF-15, and 1.10 (95% CI 1.00, 1.21; p = 0.042) per SD increase in GDF-15." (PMID 30350239, 2019). "If participants were grouped according to baseline fasting glucose, the association between GDF-15 and diabetes risk was only evident in the group without impaired fasting glucose (n = 3973)." (PMID 30350239, 2019). "The complexity of the relationship between ageing and GDF-15 expression could at least partly explain why the strength of the association that we observed between GDF-15 and diabetes risk changed with age and with follow-up duration." (PMID 30350239, 2019). "GDF‐15 levels might be influenced by many factors, including age, gender, smoking status, diabetes mellitus and so on." (PMID 30652072, 2019). "Moreover, regarding categorical variables, GDF-15 levels were significantly related to the hypertension (1600.8 ± 830.9 ng/l vs. 1097.6 ± 590.3 ng/l, p = 0.037) and diabetes (1668 ± 269.1 ng/l vs. 1379 ± 123.5 ng/l, P = 0.006)." (PMID 27311391, 2016).
diabetes (continued). "Similarly Adela and Banerjee in their review paper recognized the relation of high levels of GDF-15 with diabetes, anemia of various etiology, and other comorbidities." (PMID 27043030, 2016). "Further understanding regarding the signaling pathways of GDF-15 may help to discover novel therapies against diabetes and cardiovascular complications." (PMID 26273671, 2015). "GDF-15 is patented as a biomarker for the type 1 diabetes and diabetes related heart diseases." (PMID 26273671, 2015). "In other words, not only active intervention, such as nutritional therapy, rehabilitation, and diabetes control normalize GDF15, but also direct GDF15 suppression may also improve cancer inducing anorexia, one of the causes of cachexia, and decrease postoperative complications." (PMID 41016991, 2026). "It remains to be seen if GDF15's association with T1DM is causal or related to the secondary systemic inflammation seen with diabetes, but better understanding of the role of GDF15 in glucose metabolism and diabetes is important and warrants further investigation." (PMID 40019842, 2025). "However, the role of GDF15 in cardiovascular diseases, diabetes, metabolic liver diseases, and other disorders remains unclear and controversial, with conflicting research results, thus necessitating more evidence to support these findings." (PMID 40837873, 2025). "GDF15, due to its sensitivity to metabolic signals and its function in inhibiting tumor-promoting stromal dynamics, presents a valuable molecular target for comprehensive therapeutic approaches, especially in individuals with metabolic comorbidities like diabetes." (PMID 41009692, 2025). "GDF15's role in metabolism may prove critical to better understand diabetes and childhood obesity." (PMID 40019842, 2025). "Moreover, the presence of multiple comorbidities (e.g., hypertension, diabetes, renal failure) in all patients may have influenced GDF15 levels." (PMID 40941711, 2025). "Thus, the presence of polypharmacy resulting from prolonged diabetes duration may also have influenced plasma GDF15 levels in our study." (PMID 38965822, 2024). "The AUC of total GDF15 was positively correlated with large and very large triglyceride-rich lipoprotein particles, the triglyceride size (TRLZ), isoleucine, alanine, and glutamine, ketone bodies, acetone, and the Lipoprotein Insulin Resistance (LP-IR) Score and Diabetes Risk Index (DRI)." (PMID 38762719, 2024). "A positive association between GDF15 with A1C, triglycerides, glucose levels, and homeostatic model assessment of insulin resistance (HOMA‐IR), but negative correlation with insulin sensitivity in morbidly obese subjects with diabetes were previously demonstrated." (PMID 39668628, 2024). "Moreover, ablation of GDF15 lowers ER stress-induced β-cell apoptosis in diabetes." (PMID 37745718, 2023). "A recent proteomic study revealed an increase in plasma GDF-15 by empagliflozin in patients with diabetes or impaired glucose tolerance, however, it is unknown whether the SGL2Ti mediated improvement of HFrEF is accompanied by a change in plasma of GDF-15 levels." (PMID 35219331, 2022). "Growth differentiation factor 15 (GDF15), a member of the tumor growth factor (TGF) superfamily, has recently been identified as a possible aging biomarker and has been linked to a variety of clinical conditions, including coronary artery disease, diabetes, and multiple cancer types." (PMID 35806043, 2022). "Similarly a further study using genetic instruments weakly correlated to rs1058587 (strongest R2 ≤ 0.02) found no significant causal effect of GDF15 levels on BMI or diabetes traits." (PMID 35916366, 2022). "For example, GDF-15 is also associated with increased risk of incident diabetes, which is also a risk factor for non-lobar ICH, and this could hypothetically explain part of the association with non-lobar ICH." (PMID 34177769, 2021).